SRC (SRC proto-oncogene, non-receptor tyrosine kinase)
Diseases named in the same sentence as SRC in open-access papers (continued):
Sharing a sentence is not in itself a finding about the gene and the disease.
liver cancer (27 papers, 2015 to 2025). An epithelial or non-epithelial malignant neoplasm that arises from the liver. "We demonstrated that c-Src kinase promoted liver cancer development, and the expression of SRC (encodes c-Src kinase) was positively correlated with METTL3 in liver cancer cases." (PMID 40612868, 2025). "In this study, we bridged the association between SRC and METTL3 according to publicly available liver cancer datasets with clinical data and functional analyses revealed that METTL3 modulates SRC mRNA expression through m6A-dependent mechanisms." (PMID 40612868, 2025). "The stable binding of SRC to the active compound was confirmed by molecular docking results, which further confirmed its anti-liver cancer properties." (PMID 39806972, 2025). "We further provided evidence showing that IRF1 was a novel transcription factor of SRC, and the IRF1/c-Src axis participated in METTL3-promoted proliferation of liver cancer cells." (PMID 40612868, 2025). "Clinical data analysis showed a positive correlation between both METTL3/SRC and METTL3/IRF1, as well as the OS of liver cancer patients associated with METTL3/SRC expression." (PMID 40612868, 2025). "When exploring the core genes’ expression in the GEPIA database, we found that ESR1 gene expression was significantly reduced in liver cancer patients, while SRC gene expression was significantly increased in liver cancer compared to healthy people." (PMID 40508014, 2025). "Together, results showed that both SRC and METTL3 were associated with worse survival of liver cancer patients." (PMID 40612868, 2025). "Future studies should focus on the differences in the binding affinity of luteolin with AKT1 and SRC to identify the protein that functions independently in the inhibition of liver cancer when using luteolin to further enhance its use." (PMID 39234106, 2024). "The SRC expression has been positively related to tumor stage and metastasis has indicated this kinase as a potential target in liver cancer." (PMID 37765047, 2023). "In this study, some potential active compounds such as Obacunone, Beta-sitosterol, Sitosterol, and others were screened using network pharmacology, and SRC was clearly identified as the most promising target of EF in the treatment of liver cancer." (PMID 36700075, 2022). "Together, results indicated that METTL3 modulated the transcription of SRC in liver cancer cells." (PMID 40612868, 2025). "Saracatinib, an SRC inhibitor, might improve the outcomes of liver cancer patients and have been approved by the food and drug administration organization for the treatment of HCC." (PMID 35452485, 2022). "SRC-mediated co-activation of anti-tumor target genes inhibits MYC-induced liver cancer." (PMID 35991574, 2022). "In addition, SRC inhibitors can treat liver fibrosis and liver cancer." (PMID 37165407, 2023). "For example, the KEGG enrichment analysis results of SRC show that it is enriched in the item of cellular adhesion, so basic experiments can be used to verify whether SRC has an effect on the invasion and metastasis of liver cancer cells.." (PMID 33274225, 2020). "Together, these data suggested that SRC mRNA can be m6A modified via METTL3, and METTL3 upregulated the expression of c-Src in liver cancer cells." (PMID 40612868, 2025). "According to GEPIA2 analysis, there was a significant positive correlation between SRC and METTL3 expression in liver cancer tissues was observed (r = 0.41; p = 4.40 × 10−16)." (PMID 40612868, 2025). "Our results systematically elucidate the mechanism of luteolin in inhibiting the proliferation of liver cancer cells, mainly through cell cycle arrest and apoptosis via targeting AKT1 and SRC." (PMID 39234106, 2024). "Our results systematically elucidate the mechanism of luteolin in inhibiting liver cancer cells, mainly through cell cycle arrest and apoptosis via targeting AKT1 and SRC." (PMID 39234106, 2024).
liver cancer (continued). "Further research studies revealed that SRC was highly expressed in HCC, which was consistent with our result of SRC mRNA expression level in liver cancer." (PMID 37900162, 2023). "SRC has been found to be overexpressed in HCC, and SRC inhibitors are a first-line chemotherapeutic treatment for liver cancer, although some patients are refractory to the treatment." (PMID 30341289, 2018). "In addition, the expression of IRF1 was positively correlated to both SRC and METTL3 in liver cancer patients, p = 6.60 × 10−5 and p = 4.10 × 10−4, respectively." (PMID 40612868, 2025). "To analyze the potential role of c-Src in liver cancer, we first examined the SRC (code for c-Src) mRNA expression levels in the tumor and normal tissues from liver cancer patients of TCGA series of cases based on Gene Expression Profiling Interactive Analysis 2 (GEPIA2) database." (PMID 40612868, 2025). "Next, the potential linkage between SRC and METTL3 in liver cancer was investigated." (PMID 40612868, 2025). "Through the construction of a protein interaction network and screening and verification of core targets, it was found that CDK1, SRC, CDK4 and E2F1 mRNA and protein expression levels were overexpressed in liver cancer tissues compared with normal liver tissues." (PMID 36699068, 2022).
bladder cancer (22 papers, 2002 to 2025). "Next, potential integrated prognosis-related proteins (IPRPs) model (including BECLIN, PKCALPHA, EGFR, ANNEXIN1, AXL and SRC) was constructed to assess the survival risk score of bladder cancer." (PMID 33830879, 2021). "Within the pathways associated with glyphosate-induced kidney injury, the bladder cancer pathway exhibits the lowest p-value, highlighting genes such as MMP9, MMP2, and SRC." (PMID 40851020, 2025). "Here, we demonstrate that SRC expression in primary and metastatic bladder cancer negatively correlates with innate immune gene expression and immune cell infiltration." (PMID 37166992, 2023). "In conclusion, we present the first evidence of HME’s anti-bladder cancer effect, likely proceeding by evoking apoptosis through suppression of the antiapoptotic SRC/STAT3/survivin signaling axis." (PMID 36613579, 2022). "Collectively, these data supported that HME blocks STAT3 activation by suppressing SRC activity in bladder cancer cells." (PMID 36613579, 2022). "In conclusion, we first report HME’s cytotoxic effect on human bladder cancer cells via suppression of the antiapoptotic SRC/STAT3/survivin signaling axis." (PMID 36613579, 2022). "To determine the underlying mechanism of PDK4 in bladder cancer, we evaluated the expression of migration- and invasion-related proteins, p-ERK p-SRC, and p-JNK." (PMID 36362028, 2022). "This cytotoxic action is attributed to the induction of bladder cancer cell apoptosis by thwarting the antiapoptotic SRC/STAT3/survivin signaling axis." (PMID 36613579, 2022). "This study aims to identify potential prognostic biomarkers of bladder cancer (BCa) based on large-scale multi-omics data and investigate the role of SRC in improving predictive outcomes for BCa patients and those receiving immune checkpoint therapies (ICTs)." (PMID 33830879, 2021). "The circular RNA circFNDC3B reduces bladder cancer progression through the miR-1178-3p/G3BP2/SRC/FAK axis." (PMID 34322376, 2021). "However, SRC is overexpressed in various solid tumors, including breast, pancreatic, gastric, and bladder cancers, where it accelerates tumor cell growth and survival." (PMID 41017855, 2025). "Next, we sought to determine whether p-c-SRC correlated with pSMAD2C in a collection of bladder cancer patient-derived samples." (PMID 31554791, 2019). "For instance, SRC has a role in 26 pathways, some of them actually related to cancer (hsa04012 [ErbB signaling pathway], hsa05203 [viral carcinogenesis], hsa05205 [proteoglycans in cancer], hsa05219 [bladder cancer])." (PMID 29530003, 2018). "Interesting, SRC has been reported as a target gene of miR-203 in bladder cancer." (PMID 25140799, 2014). "In addition, we showed that NIBAN1 could regulate FAK and its downstream SRC/AKT signaling activation in bladder cancer cell line models." (PMID 35281857, 2022). "Furthermore, our observations suggest that c-SRC inhibitor monotherapy may function to prevent invasion and metastasis in high-grade T1 stage bladder cancers particularly in BCG refractory patients." (PMID 31554791, 2019). "The results showed that compared with normal tissues, ESR1, PTGS2 and BCL2 in bladder cancer tissues were significantly down-regulated; CASP3, INS, SRC, CDK4, GSK3B and ERBB2 were significantly up-regulated." (PMID 41287122, 2025). "To evaluate the role of PDK4 in bladder cancer, we suppressed PDK4 expression, and downregulated PDK4 reduced the migratory capacity and invasiveness of bladder cancer cells by modulating p-ERK, p-SRC, and p-JNK." (PMID 36362028, 2022). "Altogether, the evidence supports that HME represses the SRC/STAT3/survivin signaling axis to inhibit cell viability and clonogenicity of bladder cancer cells, consequently exerting cytotoxicity." (PMID 36613579, 2022). "Based on our results, PDK4 plays a critical role in the metastasis and growth of bladder cancer cells through changes in ERK, SRC, and JNK." (PMID 36362028, 2022).
bladder cancer (continued). "Given that SRC activation was inhibited in all HME-treated bladder cancer cell lines, we figured SRC is the primary target of HME for blocking STAT3 activation, in turn promoting bladder cancer cytotoxicity." (PMID 36613579, 2022). "The bladder cancer category included proteins such as MAPK1 (P28482), EGFR (E9PFD7), SRC (P12931), and ERBB2 (B4DTR1)." (PMID 36362028, 2022). "In bladder cancer cell lines, it was observed that curcumin up-regulated the expression of miR-203 and in turn decreased the expression of AKT2 and SRC." (PMID 33292283, 2020). "It is also worth noting that our discovery about SRC inhibition by HME implies that, besides STAT3, additional signaling pathways downstream of SRC, such as AKT and MAPK, are likely involved in HME’s anticancer mechanisms of action in the context of bladder cancer." (PMID 36613579, 2022). "Our inquiry about how HME suppresses STAT3 activation revealed that SRC appears as the primary STAT3 upstream kinase targeted by HME, as the levels of tyrosine 416-phosphorylated SRC were markedly lowered in all HME-treated bladder cancer cell lines." (PMID 36613579, 2022). "Besides, circFNDC3B competitively binds to miR-1178-3p, resulting in decreased expression of G3BP2, and then inhibits the downstream SRC/FAK signaling pathway to impair tumor growth and lymphatic metastasis in bladder cancer." (PMID 34782720, 2022). "First, SMURF2 inhibition by c-SRC upregulates the TβR pathway by stabilising TGFβR complex a function we define to be critical for HGF-induced EMT and invasion in vitro and tumour progression in vivo in bladder cancer." (PMID 31554791, 2019).
breast tumors (22 papers, 2008 to 2025). "Analyses of invasive breast tumor data sets indicate an inverse correlation of high RASSF1A methylation/low pS127-YAP1 with SRC activation and the expression of invasion-associated transcripts." (PMID 26549256, 2015). "To examine the associations of SRC expression level with the molecular subtypes of BCs, we first evaluated SRC mRNA expression in breast tumors from the cancer genome atlas (TCGA)-BRCA datasets, including 114 normal tissues and 1097 primary BC tumor tissues." (PMID 36633714, 2023). "The expression and activity of SRC or PIK3R1 are highly upregulated in malignant breast tumor tissues and have been correlated with decreased survival of BC patients." (PMID 33628298, 2021). "The relationship between SRC activation and patient response to trastuzumab-based therapies was previously studied in a cohort of 57 patients who were evaluated for SRC activation in primary breast tumors." (PMID 26824988, 2016). "RASSF1A restricts SRC activity, preventing motility, invasion, and tumorigenesis in vitro and in vivo, with epigenetic inactivation correlating with increased inhibitory pY527-SRC in breast tumors." (PMID 26549256, 2015). "Many SRC-dependent sites identified in our study were tyrosine phosphorylated in these human breast tumors." (PMID 21049007, 2010). "Thus, Ifng from SRC-3 KO Tregs elevates Cxcl9 expression in E0771 breast tumors in SRC-3d/d:Treg female mice and suppresses the growth of breast tumors." (PMID 37253006, 2023). "Therefore, SRC-3 KO Tregs induced with tamoxifen treatment eradicate breast tumors in SRC-3d/d:Treg female mice." (PMID 37253006, 2023). "In addition, we noticed that SRC expression level was highly related to breast tumor node metastasis (TNM) stage, and the BC tissues at stage III usually had a higher IHC score." (PMID 36633714, 2023). "This suggests that the treatment strategy for managing ESR1-CCDC170 positive breast tumors may depend on the context of HER2 and SRC expressions which calls for further studies to elucidate." (PMID 32771039, 2020). "However, several putative SRC substrates, including HIPK3, STAT5A, p120, FRK and Hrs, were frequently phosphorylated in multiple breast tumors." (PMID 21049007, 2010). "The pathway, characterized by the formation of ER/SRC/PI3K and the subsequent activation of AKT, is present in normal breast tissue and is hyperactivated in aggressive breast tumors." (PMID 33503805, 2021).
triple-negative breast carcinoma (20 papers, 2013 to 2025). An invasive breast carcinoma which is negative for expression of estrogen receptor (ER), progesterone receptor (PR), and human epidermal growth factor receptor 2 (HER2). "For instance, inhibiting SRC activity with dasatinib sensitizes triple-negative breast cancer cells to chemotherapy by suppressing epithelial-to-mesenchymal transition." (PMID 39859167, 2025). "For example, an unbiased genome-wide CRISPR-Cas 9 screen in triple-negative breast cancer revealed that loss of ILK and its binding partners α-parvin and PINCH-1 potentiated the inhibitory effect of bosutinib, a SRC/ABL kinase inhibitor." (PMID 37508338, 2023). "SRC-mediated escape of ETS-1 from COP1 has implications in triple-negative breast cancer (TNBC), where a significant correlation was found in tissue samples between SRC phosphorylation and ETS-1 protein levels." (PMID 34066106, 2021). "In addition to MCF10A cells, TGF-β-induced SRC expression was also observed in the triple-negative breast cancer cell line BT-549." (PMID 37439249, 2023). "More recently, it has been shown that inhibition of CPT1 and fatty acid oxidation reduces the activation of the proto-oncogene SRC, including mitochondrially-localized SRC, to result in reduced in vitro and in vivo triple-negative breast cancer cell and tumor growth." (PMID 33413672, 2021). "It has been shown that the SRC inhibitor PP2 effectively blocks the growth and EMT of triple-negative breast cancer cell lines." (PMID 39859167, 2025).
atherosclerosis (19 papers, 2016 to 2026). A disease characterized by the build-up of fatty material and calcium deposition in the arterial wall resulting in partial or complete occlusion of the arterial lumen. "It posits that primary active ingredients of THL – quercetin, salidroside, and oleanolic acid – may exert effects on targets like ALB, EGFR, SRC, potentially modulating pathways associated with cancer, lipid and atherosclerosis, and IL-17 signaling in the context of PN intervention." (PMID 38905418, 2024). "In this study, EGFR, VEGFA, HSP90AA1, SRC, HIF1A, CXCR4 and IGF1R were identified as key hub targets, which linked anthocyanins with atherosclerosis." (PMID 40478326, 2025). "Potential targets such as GAPDH, AKT1, TNF, IL6, and SRC were implicated in key pathways including MAPK signaling pathway, lipid and atherosclerosis, PI3K-Akt signaling pathway, and IL-17 signaling pathway." (PMID 39822742, 2024). "The experiment verified the SRC as key targets have a regulating effect on atherosclerosis." (PMID 38515732, 2024). "Network pharmacology and molecular docking results revealed that several blood-brain barrier (BBB)-permeable active components of Lonicera caerulea, including Naringenin and Palmatine, may be associated with targets involved in the lipid and atherosclerosis pathway, such as HSP90AA1, SRC and TNF." (PMID 42196534, 2026). "In atherosclerosis, the expression levels of CD36, PPARG, MMP9 and SRC were upregulated, while NOB inhibited their expression." (PMID 38468335, 2024). "Firstly, we demonstrated that RSV might inhibit ferroptosis to exert anti‐atherosclerosis effect; In addition, RSV regulates ferroptosis mainly through six biomarkers, including IL1B, RELA, HIF1A, SRC, PTEN, and MAPK1, in AS treatment." (PMID 40697701, 2025). "Our results indicated that compounds in Tualang honey such as luteolin, fisetin, hesperitin, catechin, and kaempferol may have a crucial impact on atherosclerosis through their effects on key biological targets, including PIK3CA, SRC, P1K3R1, EGFR, PTPN11, and AKT1." (PMID 37174317, 2023).
diabetes (19 papers, 2010 to 2026). "In the context of diabetes pathogenesis, SRC, FYN, and EGFR are significantly implicated in the development of vascular complications, such as diabetic kidney injury, and have been reported to prevent/improve diabetic nephropathy and other diabetic-related kidney injuries." (PMID 41011980, 2025). "SRC is one of the key regulators of lipid metabolism and diabetes pathogenesis." (PMID 34648514, 2021). "Consistent with our results, Sampath reported that TRX may play a significant role in the management of type 2 diabetes mellitus by improving insulin signaling molecules, including the SRC, Akt and GLUT4 proteins." (PMID 31182097, 2019). "Additionally, SRC plays a role in the pathogenesis of CS in diabetes." (PMID 37985432, 2024). "Key targets such as JUN, AKT1, ESR1, CASP3, TNF, SRC, and IL6 were identified as central regulators in diabetes-related pathways, with molecular docking confirming strong binding interactions between Chaga-derived phytochemicals and these targets." (PMID 40508014, 2025). "SRC/EGFR/FYN, on the other hand, provides some therapeutic leverage, but it more specifically addresses diabetes-related complications." (PMID 41011980, 2025). "Among these, seven key targets (JUN, AKT1, ESR1, CASP33, TNF, SRC, and IL6) were found to have the highest network connectivity, indicating their central role in treating diabetes with Chaga." (PMID 40508014, 2025). "In addition, the cytoHubba plug-in has identified four key targets (HSP90AA1, AKT1, SRC, and MAPK1) that have a significant connection to the pathogenesis and treatment of type 2 diabetes mellitus." (PMID 38031191, 2023). "Our results uncovered that AS-IV can protect retinal cells against diabetes induced retinopathy, which may act on target proteins AKT1, CASP3 and HIF1α, VEGFA, IL6, IL1β, SRC and CTNNB1, and might be involved in the regulation of PI3K-AKT signaling pathway." (PMID 35814228, 2022).